Y_RNA (Y RNA )
Gene: Miscellaneous RNA gene on chromosome X (115,139,030 to 115,139,123, reverse strand). Ensembl gene ENSG00000212241.
Homologues: Orthologues: chimpanzee Y_RNA (99% identical), macaque Y_RNA (93% identical), guinea pig Y_RNA (64% identical). Paralogues in human: Y_RNA (85% identical), Y_RNA (84% identical), RNY3 (83% identical), Y_RNA (83% identical), Y_RNA (82% identical), RNY3P14 (81% identical), RNY3P2 (81% identical), Y_RNA (81% identical), RNY3P1 (80% identical), RNY3P9 (80% identical), Y_RNA (80% identical), Y_RNA (79% identical), and 87 more.